SLC27A4 (solute carrier family 27 member 4)
Description:
Mediates the levels of long-chain fatty acids (LCFA) in the cell by facilitating their transport across cell membranes. Appears to be the principal fatty acid transporter in small intestinal enterocytes. Also functions as an acyl-CoA ligase catalyzing the ATP-dependent formation of fatty acyl-CoA using LCFA and very-long-chain fatty acids (VLCFA) as substrates, which prevents fatty acid efflux from cells and might drive more fatty acid uptake. Plays a role in the formation of the epidermal barrier. Required for fat absorption in early embryogenesis (By similarity). Probably involved in fatty acid transport across the blood barrier. Indirectly inhibits RPE65 via substrate competition and via production of VLCFA derivatives like lignoceroyl-CoA. Prevents light-induced degeneration of rods and cones (By similarity).
Synonyms: FATP-4; ACSVL4; FATP4; IPS
Tractability: Small molecule: a high-quality ligand is known; it belongs to a druggable protein family. Antibody: its Gene Ontology location is reachable by antibodies, with high confidence; UniProt predicts a signal peptide or a membrane-spanning region. PROTAC: ubiquitination databases record sites on it; its protein half-life has been measured; a small molecule that binds it is known.
Target class: Electrochemical transporter; Transporter; SLC27 family of fatty acid transporters; SLC superfamily of solute carriers
Gene: Protein-coding gene on chromosome 9 (128,340,506 to 128,363,283, forward strand). Ensembl gene ENSG00000167114.
Subcellular location: Endoplasmic reticulum membrane
Subcellular location (Human Protein Atlas): Vesicles
Pathways (Reactome):
Disease: Defective SLC27A4 causes ichthyosis prematurity syndrome (IPS)
Transport of small molecules: Transport of fatty acids
Gene Ontology:
Molecular function: long-chain fatty acid transmembrane transporter activity; long-chain fatty acid-CoA ligase activity; oleoyl-CoA ligase activity; palmitoyl-CoA ligase activity; fatty acid transmembrane transporter activity; arachidonate-CoA ligase activity; very long-chain fatty acid-CoA ligase activity
Biological process: fatty acid metabolic process; fatty acid transport; lipid transport across blood-brain barrier; long-chain fatty acid import into cell; long-chain fatty acid metabolic process; long-chain fatty acid transport; negative regulation of insulin receptor signaling pathway; positive regulation of apoptotic process; glucose import in response to insulin stimulus; medium-chain fatty acid transport; transport across blood-brain barrier; response to nutrient
Cellular component: endoplasmic reticulum; endoplasmic reticulum membrane; membrane; plasma membrane; brush border membrane; microvillus
Genetic constraint (gnomAD): Loss-of-function variants: 32 observed, 64.98 expected, observed/expected ratio (o/e) 0.49, 90% interval 0.37 to 0.66. The upper end of that interval is the gene's LOEUF score, 0.66, which puts it in group 2 of 6, group 1 being the genes least tolerant of losing a copy. Missense variants: 823 observed, 916.9 expected, observed/expected ratio (o/e) 0.9, 90% interval 0.85 to 0.95. Synonymous variants: 377 observed, 387.26 expected, observed/expected ratio (o/e) 0.97, 90% interval 0.89 to 1.06.
Homologues: Orthologues: chimpanzee SLC27A4 (98% identical), macaque SLC27A4 (98% identical), mouse Slc27a4 (92% identical), guinea pig SLC27A4 (91% identical), rat Slc27a4 (91% identical), pig SLC27A4 (91% identical), rabbit SLC27A4 (86% identical), dog SLC27A4 (83% identical), tropical clawed frog slc27a4 (72% identical), zebrafish slc27a4 (70% identical), Drosophila melanogaster Fatp1 (46% identical), Drosophila melanogaster Fatp2 (45% identical), and 22 more. Paralogues in human: SLC27A1 (62% identical), SLC27A2 (39% identical), SLC27A6 (38% identical), SLC27A5 (38% identical), SLC27A3 (38% identical), ACSL1 (20% identical), ACSL6 (19% identical), ACSL3 (18% identical), ACSL4 (18% identical), ACSL5 (18% identical), ACSBG2 (16% identical), ACSBG1 (16% identical).
Diseases named in the same sentence as SLC27A4 in open-access papers:
SLC27A4 is named in the same sentence as 54 diseases in open-access papers, as found by Europe PMC text mining. Sharing a sentence is not in itself a finding about the gene and the disease. The quoted sentences say what the papers report.
Obesity (20 papers, 2009 to 2025). Accumulation of substantial excess body fat. "On the other hand, in a rat model of diet-induced obesity that is associated with IUGR, mRNA and protein levels of CD36, Slc27a1/Fatp1 and Slc27a4/Fatp4 were reported as decreased relative to control." (PMID 31774824, 2019). "A SNP in ELOVL3 showed potential association with both type 2 diabetes, fasting plasma glucose and waist circumference while two SNPs in ACP1 and SLC27A4 were selected from analyses of obesity, BMI and waist circumference." (PMID 23160641, 2013). "In human studies, links between both SLC27A1 and SLC27A4, and obesity and T2D have been proposed." (PMID 25784953, 2015). "In general, obesity translated into a greater content of fatty acid transporters (especially CD36/SR-B2 and SLC27A4/FATP4) and boosted accumulation of all the examined lipid fractions, i.e., triacylglycerols (TAGs), diacylglycerols (DAGs), and free fatty acids (FFAs)." (PMID 37602323, 2023).
ichthyosis prematurity syndrome (11 papers, 2011 to 2025). Ichthyosis prematurity syndrome is a rare, syndromic congenital ichthyosis characterized by premature birth (at gestational weeks 30-32, in general) in addition to thick, caseous and desquamating epidermis, neonatal respiratory asphyxia, and persistent eosinophilia. "Furthermore, SLC27A4 was found to be involved in neurological disorders as well as Ichthyosis prematurity syndrome." (PMID 40384935, 2025). "FATP4 is encoded by the SLC27A4 gene, the mutations of which lead to syndromic autosomal recessive ichthyosis prematurity syndrome (IPS), one of the disorders commonly referred to as ARCI." (PMID 34497816, 2021). "FATP4 (SLC27A4) mutations cause ichthyosis prematurity syndrome, a nonlethal disorder." (PMID 31519952, 2019).
Hepatic steatosis (9 papers, 2015 to 2025). Steatosis is a term used to denote lipid accumulation within hepatocytes. "In addition, long-term (8–17 weeks) supplementation of AMF suppresses hepatic steatosis with decreasing lipogenesis-related gene expression, including Cebpa, Fabp4, and Slc27a4 in HFD-fed mice." (PMID 35454963, 2022).
hepatocellular carcinoma (9 papers, 2019 to 2025). A malignant tumor that arises from hepatocytes. "For example, overexpression of SLC27A4, also known as FATP4, inhibits ferroptosis in hepatoma cells by significantly enhancing selective uptake of MUFAs." (PMID 39218897, 2024). "Similarly, solute carrier family 27 member 4 (SLC27A4)-mediated uptake of MUFA facilitates the resistance to ferroptosis triggered by sorafenib in hepatocellular carcinoma." (PMID 39624080, 2024). "Similarly, studies on hepatocellular carcinoma (HCC) cells have demonstrated that SLC27A4 is crucial for the proliferation and invasion of these cells." (PMID 37239243, 2023).
ichthyosis (9 papers, 2012 to 2026). Disorders of cornification that are characterized by visible scaling and/or hyperkeratosis of most or all of the skin. "Ichthyosis prematurity syndrome (IPS) is a rare autosomal recessive congenital ichthyosis caused by variants of the SLC27A4 gene." (PMID 41409931, 2025). "In conclusion, we identified a SLC27A4 missense variant as the most likely causative mutation for ichthyosis in Great Danes." (PMID 26506231, 2015). "Both mutations detected in SLC27A4 were genotyped in 28 Great Danes including the detection sample (n = 22) and further six Great Danes with patho-histologically confirmed ichthyosis." (PMID 26506231, 2015). "Analyses of skin biopsies in ichthyosis patients suggested the mutant SLC27A4 protein to induce an uneven distribution of lipids and disturb the formation of the skin barrier." (PMID 26506231, 2015). "Dermatology evaluation raised concern for ichthyosis versus severe atopic dermatitis, and genetic testing was nondiagnostic except for a variant of uncertain significance in SLC27A4." (PMID 42292717, 2026). "We found that all 15 ichthyosis-affected Great Danes were homozygous for SLC27A4:g.8684G>A mutant allele A whereas none of the genotyped 413 dogs of 35 different breeds and seven wolves showed a SNV allele different from the wild type." (PMID 26506231, 2015).
breast carcinoma (8 papers, 2018 to 2024). "High expression of SLC27A4 was associated with breast cancer tissues and poor prognosis in breast cancer patients." (PMID 30388870, 2018). "It suggests that the SLC27A4 expression level was also associated with migration and invasion capacity of breast cancer." (PMID 30388870, 2018). "Taken together, our results confirm that high SLC27A4 is associated with tumor progression in breast cancer cells." (PMID 30388870, 2018). "The bioinformatic analysis revealed that high SLC27A4 was associated with breast cancer tissue and poor prognosis in breast cancer patients." (PMID 30388870, 2018). "We believe that SLC27A4 is a potential diagnostic marker for breast cancer." (PMID 30388870, 2018). "This suggested that SLC27A4 is associated with enhancement of cell growth in breast cancer cells." (PMID 30388870, 2018). "The data implies that SLC27A4 might be associated with malignancy of breast cancer." (PMID 30388870, 2018). "In breast cancer cells, SLC27A4 plays a role in proliferation and epithelial-to-mesenchymal transition (EMT)." (PMID 37239243, 2023). "High levels of SLC27A4 have been detected in bladder cancer, renal cell carcinoma, and breast cancer compared to controls, whereas uterine cervical cancer has shown reduced levels." (PMID 36556492, 2022). "In breast cancer, SLC27A4 enhances the cell growth, migration, and invasion of Hs578T and MDA-MB-231." (PMID 32425696, 2020). "The analysis showed that SLC27A4-correlated genes mainly involved in metabolic processes in normal breast tissues and in transport processes in breast cancer tissues." (PMID 30388870, 2018). "Our results showed that significantly higher SLC27A4 expression was observed in all subtypes, stages, and races in breast cancer tissues when compared to normal breast tissue." (PMID 30388870, 2018). "Compared to normal breast tissues, most breast cancer tissues revealed median to high SLC27A4 expression." (PMID 30388870, 2018). "Silencing SLC27A4 expression significantly reduced uptake of free fatty acids in two breast cancer cell lines, Hs578T and MDA-MB-231." (PMID 30388870, 2018). "The SLC27A4 expression was evaluated by Western blot assay in luminal A breast cancer cell lines T47D and MCF-7, and triple negative breast cell lines Hs578T and MDA-MB-231." (PMID 30388870, 2018). "The SLC27A4 protein expression in normal breast and breast cancer tissues were also evaluated by the Human Protein Atlas database." (PMID 30388870, 2018). "In high SLC27A4-expressing breast cancer tissues and low SLC27A4-expressing normal breast tissues, different biological processes were observed." (PMID 30388870, 2018). "In addition, our results suggest that silencing SLC27A4 expression inhibited cell growth, migration and invasion capacity in breast cancer cell lines." (PMID 30388870, 2018). "Because SLC27A4 is a transmembrane protein, blockage of extracellular SLC27A4 via a SLC27A4 antibody might be a novel therapeutic strategy against breast cancer due to disruption of the SLC27A4/CD36-mediated fatty acids transportation pathway." (PMID 30388870, 2018). "In addition, there is a trend toward shorter overall survival and distant metastasis-free survival in breast cancer patients with higher SLC27A4 expression (p = 0.0725 and 0.033 respectively)." (PMID 30388870, 2018). "Moreover, bioinformatic analyses suggest that SLC27A4 is involved in regulation of cell size in breast cancer cells." (PMID 30388870, 2018). "These evidences might provide a possible interacting network of SLC27A4 in clinical breast cancer tissues." (PMID 30388870, 2018). "BRAF is involved in the processes of EMT, stemness or metastasis in breast; thus, different BRAF status in two breast cancer cell lines might affect the EMT signaling pathways after SLC27A4 silencing." (PMID 30388870, 2018).
breast carcinoma (continued). "In addition, fatty acid metabolism is important in regulating breast cancer progression, solute carrier family 27 member 4 (SLC27A4), as a fatty acid transporter, is also highly expressed in T2DM samples, and it is worthy of further study whether SLC27A4 can be used as a diagnosis of T2DM." (PMID 39096856, 2024). "Although detailed regulatory signaling pathways of SLC27A4 was not completely investigated in this study, our results firstly demonstrated that SLC27A4 was involved in progression of breast cancer." (PMID 30388870, 2018). "There are no related studies indicating the interacting networks of SLC27A4 in breast cancer." (PMID 30388870, 2018).
lung carcinoma (5 papers, 2018 to 2023). "In lung cancer cell lines, SLC27A4 directly interacts with autophagy-related 4B cysteine peptidase (ATG4B)." (PMID 30388870, 2018). "In lung cancer cells, SLC27A4 is responsible for chemoresistance." (PMID 37239243, 2023). "SLC27A4 is also overexpressed in lung cancer cell lines as well as lung tumor tissues." (PMID 32425696, 2020). "Finally, in human lung cancer cells, ATG4B directly interacted with soluble carrier family 27 member 4 (SLC27A4) to form a SLC27A4/ATG4B complex, and knockdown of SLC27A4 could decrease the ATG4B level, thus enhancing the therapeutic efficiency of chemotherapeutic drugs." (PMID 31083460, 2019).
steatosis (5 papers, 2015 to 2025). Increased lipid within the cytoplasm of cells. "Interestingly, the expression of liver fatty acid transport-related genes, including SLC27A4, ACBD3 and SLC27A1, were significantly reduced in FFA induced steatosis cells or HFD induced steatotic liver compared with control groups." (PMID 26330104, 2015).
diabetes (4 papers, 2013 to 2024). "At E10.5, effects of diabetes were significant for Slc27a6/Fatp6, Slc27a4/Fatp4, and Cpt2 (27.8%, 19.4%, and 19.7%, respectively), and for Cpt1a, Slc2a13/Glut13, and Cpt1b, diet was a significant contributor (42.9%, 38.7%, and 31%, respectively)." (PMID 31774824, 2019). "In addition, CD36 and Slc27a4/Fatp4 expression levels, while not influenced by diabetes, were strongly responsive to diet (40.6% and 82.1%, respectively)." (PMID 31774824, 2019).
metabolic syndrome (4 papers, 2015 to 2023). A cluster of metabolic risk factors for CARDIOVASCULAR DISEASES and TYPE 2 DIABETES MELLITUS. "Thus, our findings of an association between the SLC27A4 Ser209 allele and ASD may link metabolic syndrome to ASD at the molecular level." (PMID 26548558, 2015).
hyperlipidemia (3 papers, 2022 to 2025). "Analogously, the specific and high-level expression of Slc27a4/Fatp4 in visceral endoderm prompts the hypothesis that hyperlipidemia may affect cells in the visceral yolk sac directly." (PMID 35478964, 2022). "As for the negatively correlated proteins (Fabp2, Slc27a4, Me1), they are mainly involved in lipid uptake and lipid biosynthesis, which indicates hyperlipidemia might inhibit the formation of HDL-c." (PMID 36234935, 2022).
breast tumor (2 papers, 2018 to 2023). "Higher expression of SLC27A4 in breast tumors is associated with worse prognosis, particularly with distant metastasis-free survival." (PMID 37239243, 2023). "In general, SLC27A4 mRNA expression in breast tumor tissues was higher than that in normal breast tissues in clinical samples." (PMID 30388870, 2018). "In the present study, bioinformatic analysis revealed that relatively high SLC27A4 expression was observed in all subtypes of breast tumor tissues when compared to normal breast tissues." (PMID 30388870, 2018). "It is worth investigating the interactions among SLC27A4 and these genes in breast tumor cells and tumor environment in future studies." (PMID 30388870, 2018).
autism (1 paper, 2015). Persistent deficits in social interaction and communication and interaction as well as a markedly restricted repertoire of activity and interest as well as repetitive patterns of behavior. "We compared the Autism Diagnostic Interview-Revised (ADI-R) scores among genotypes (G209/G209, G209/S209, S209/S209) of the SLC27A4 variant in female ASD patients." (PMID 26548558, 2015).
autism spectrum disorder (1 paper, 2025). A spectrum of developmental disorders that includes autism, and Asperger syndrome. "Accordingly, it has been described that alteration in fatty acid uptake within the human fetal brain, potentially influenced by the SLC27A4 dysfunction, could contribute to autism spectrum disorder pathophysiology." (PMID 40634107, 2025).
glioblastoma (1 paper, 2023). The most malignant astrocytic tumor (WHO grade IV). "Only two SLC27 genes, SLC27A3 and SLC27A4, showed a correlation between their expression in the enhancing tumor region and the tumor core of the glioblastoma." (PMID 37239243, 2023). "In female patients with glioblastoma, a positive correlation was found between the expression of SLC27A4, SLC27A5, and SLC27A6 and the number of cigarette packs smoked in their lifetime." (PMID 37239243, 2023). "This suggests that SLC27A4 may also be important in the uptake of fatty acids from the bloodstream by glioblastoma cells." (PMID 37239243, 2023). "Another enzyme described in this study that may affect outcomes in glioblastoma patients is SLC27A4." (PMID 37239243, 2023). "Drugs targeting SLC27A4 could be helpful in treating glioblastoma in low-weight men who are lean or thin." (PMID 37239243, 2023). "The expression of SLC27A4 and SLC27A6 was lower in glioblastoma tumors compared to the peritumoral area." (PMID 37239243, 2023). "In addition, a positive correlation was found between the expression of SLC27A1 and SLC27A3 in the glioblastoma tumor and between the expression of SLC27A1 and SLC27A4 in the tumor core." (PMID 37239243, 2023). "However, comparing the highest and lowest quartiles of SLC27 expression, a trend towards worse outcomes with higher expression of SLC27A4 (p = 0.062) and SLC27A3 (p = 0.083) was observed for glioblastoma patients." (PMID 37239243, 2023). "Similarly to the analysis of all patients, male samples showed a positive correlation of SLC27A1 expression with SLC27A3, SLC27A4 with SLC27A5, SLC27A4 with SLC27A6, and SLC27A5 with SLC27A6 in the studied regions of the glioblastoma tumor." (PMID 37239243, 2023). "However, GEPIA reports that SLC27A4 expression does not differ between glioblastomas and healthy brain tissue." (PMID 37239243, 2023). "In women, there was a positive correlation between the expression of SLC27A4, SLC27A5, and SLC27A6 with cigarette smoking in all investigated regions of the glioblastoma tumor and in the peritumoral area, whereas no such relationship was observed in men." (PMID 37239243, 2023).
hypothyroidism (1 paper, 2025). Abnormally low levels of thyroid hormone. "The effect of treatment (hypothyroidism) was significant for Slc27a4, Npc1l1, Slc2a2 and Slc2a5." (PMID 39958687, 2025).